CD59 (CD59 molecule (CD59 blood group))
Diseases named in the same sentence as CD59 in open-access papers (continued):
Sharing a sentence is not in itself a finding about the gene and the disease.
lymphoma (13 papers, 2013 to 2025). A malignant (clonal) proliferation of B- lymphocytes or T- lymphocytes which involves the lymph nodes, bone marrow and/or extranodal sites. "Here, we aim to investigate the mechanisms underlying the enhancing effect of RTX-IgG2 on phagocytosis when combined with other RTX isotypes and further explore its potential when combined with mAbs targeting other lymphoma antigens (CD59 and PD-L1)." (PMID 39712032, 2024). "The B-cell lymphomas differed in their expression levels of the CD20 target antigen and the complement regulatory protein CD59, and lymphomas with a higher CD20/CD59 expression ratio proved to be more sensitive for RTX-mediated CDC." (PMID 35725455, 2022). "CD59 is constitutively expressed on almost all tissues, thus protecting autologous cells from complement attack; however, in lymphomas, CD59 is over-expressed to confer resistance to complement-mediated cytolysis." (PMID 34956875, 2021). "Blocking CD59, one of the mCRPs, strongly enhanced the cytotoxic effects of rituximab against lymphoma cell lines." (PMID 28658265, 2017). "A greater CDC activity was seen in lymphoma cells with a higher CD20/CD59 expression ratio." (PMID 35725455, 2022). "By calculating the CD20/CD59 expression ratio in each cell line the lymphomas could be ranked (starting with the highest ratio) accordingly Raji/Daudi/GRANTA-519/BJAB." (PMID 35725455, 2022). "However, the only association observed in this experiment was between the expression of CD55 versus CD59 in the lymphoma cells lines, perhaps reflecting their coordinated activity in complement inhibition (R2 = 0.94)." (PMID 23638367, 2013). "Previous studies suggested that the up-regulation of complement regulation proteins (CRPs) such as CD55 and CD59 on surface of lymphoma cells inhibits the activation of complement systems, which might be the main cause of resistant cells’ unresponsiveness to Rituximab mediated CDC in vitro." (PMID 26284588, 2015). "In this work, we aimed to construct bispecific antibodies which can bind to an antigen, typically overexpressed on lymphoma cells, such as CD20, and simultaneously interact with CD59 to enhance the CDC for target-overexpressing cells." (PMID 35563599, 2022). "Bispecific antibodies targeting both CD20 and CD55 or CD20 and CD59 were also shown to potentiate the CDC of CD20-positive lymphoma cells in vitro and to prevent the growth of human lymphoma cells in SCID mice." (PMID 31024572, 2019). "Downregulation of the expression of mCRPs CD46, CD55, and CD59 improved the efficacy of rituximab and the anti-CD20 mAb ofatumumab in lymphoma and leukemia cell lines and primary CLL samples." (PMID 28658265, 2017). "Furthermore, when RTX-IgG2 is combined with other lymphoma-targeting mAbs, such as anti-CD59 or anti-PD-L1, it significantly enhances the ADCP of lymphoma cells compared to single mAb treatment." (PMID 39712032, 2024). "Neutralization of CD59 overcame resistance to RTX-mediated CDC in 2D-cultured lymphoma cells, but not in spheroids." (PMID 35725455, 2022). "Given the remarkable differences observed for the lymphoma cell lines, we subsequently assessed the functional consequences of distinct CD20, CD55 and CD59 expression for induction of complement-dependent cell lysis (CDC) induced by the different CD20-specific IgG." (PMID 33505398, 2020). "Use of a targeted CD59 inhibitor in a mouse lymphoma model decreased lymphoma growth but this approach has not yet evolved into an established clinical modality." (PMID 33271825, 2020). "Therefore, inhibiting only inducible CD59 expression in lymphoma cells but not constitutive CD59 expression in normal cells is an appropriate strategy to restore rituximab sensitivity." (PMID 34956875, 2021).
anemia (11 papers, 2011 to 2025). A reduction in the number of red blood cells, the amount of hemoglobin, and/or the volume of packed red blood cells. "Compound heterozygous mutations (one inherited and one acquired) in PIGT and germline mutations involving CD59 also lead to a PNH-like phenotype with severe anemia from marked intravascular hemolysis." (PMID 28441409, 2017). "The percentage of red blood cells with partial (type II) or total (type III) loss of CD59 is helpful in managing anaemia, as haemolysis may contribute more significantly to anaemia in patients with type III cells." (PMID 39201278, 2024). "In our case, where CD55 and CD59 testing is unavailable, the diagnosis depended solely on clinical evaluation, including typical symptoms like hemoglobinuria and anemia, and excluding bone marrow disease through biopsy." (PMID 39104998, 2024). "An in-vitro study using P. falciparum-infected RBCs demonstrated that parasitized RBCs were more resistant to complement-mediated lysis due to CD59 expression, suggesting its important role in protection from complement-mediated anaemia." (PMID 31533836, 2019). "In SLE patients with anemia, CD59 and CD35 were decreased on red blood cells." (PMID 22761633, 2012). "With decreased or a lack of CD55 and CD59 expression on their membranes, PNH red blood cells become susceptible to complement-mediated hemolysis (symptoms of which include anemia, dysphagia, abdominal pain, and fatigue), leading to thrombosis." (PMID 39273426, 2024). "However, CD59 did not decrease significantly during anaemia episodes in this or earlier studies, which imply that complement-mediated lysis is not the likely mechanism for RBC loss during malaria." (PMID 22206234, 2011). "The normal expression of CD59 in RBC of PMM2-CDG individuals observed by flow cytometry analysis, the negative results observed in the Ham’s and sucrose tests, and the absence of anemia in PMM2-CDG patients argue against quantitative and qualitative CD59 defects in these patients." (PMID 24139637, 2013).
lung carcinoma (11 papers, 2016 to 2025). "Increased expression of CD55, CD46 and CD59 has been documented in lung cancer cells while another study showed increased factor H mRNA in lung cancer biopsies." (PMID 38178176, 2024). "CD59 was reported to be highly expressed in many solid tumors such as colon cancer, lung cancer, pancreatic cancer, and ovarian cancer, while CD59 was only marginally expressed in normal cells." (PMID 33513794, 2021). "TGF-β-induced EMT in lung cancer cells was reported to confer resistance to CDC by upregulation in the CD59 expression on the surface of cancer cells." (PMID 31787848, 2019). "CD59 expression in non-small cell lung cancer tissues is much higher than in the surrounding tissue, and suggests that CD59 might be a biomarker for lung cancer progression." (PMID 31612365, 2019). "Likewise, CD59, which our analysis identified with equal abundance in lung cancer and controls, was previously identified as over-expressed in NSCLC." (PMID 26930711, 2016). "Therefore, investigators used VLPs of human JC polyomavirus (JCPyV) as a vector to carry a newly designed CD59-specific RNA expression plasmid driven by a lung-specific promoter (SP-B) for lung adenocarcinomas (pSPB-shCD59) to specifically inhibit CD59 overexpression in lung cancer cells." (PMID 34104817, 2021). "Reducing the expression of CD55 and CD59, which EGFR heightens, can trigger the complement system and enhance lung cancer sensitivity to checkpoint inhibitors." (PMID 40515636, 2025). "In human lung cancers, the levels of CD55 and CD59 were found to be adversely related to the infiltration of immune cells that combat tumors and indicated a worse prognosis." (PMID 40515636, 2025). "The expression levels of complement regulatory proteins CD46, CD55, and CD59 are notably elevated in various tumors, including head and neck squamous cell carcinoma (HNSCC), colon cancer, renal cancer, lung cancer, and breast cancer." (PMID 39958348, 2025). "The overexpression of CD59, a membrane complement regulatory protein (mCRP), induces resistance to complement-dependent cytotoxicity (CDC) activation in lung cancer cells and consequently inhibits apoptosis." (PMID 34104817, 2021). "In this study, CD59 inhibition was demonstrated to enhance the efficacy of antibody-mediated CDC and inhibit metastasis in lung cancer." (PMID 31787848, 2019). "TGF-β-induced CD59 expression during EMT is dependent on Smad3 but not on Smad2 in lung cancer A549 cells." (PMID 27548154, 2016).
viral infection (10 papers, 2014 to 2023). "Antibodies targeting CD59 provide a promising therapeutical approach against specific cancer malignancies and viral infections." (PMID 37239905, 2023). "Animal experiments or clinical studies have confirmed that CD59 can maintain the host immune homeostasis and contribute to complement resistance after inflammatory injury, tumorigenesis, and viral infection." (PMID 37050931, 2023). "In this review, we focus on two members of the Ly/uPAR-family proteins, uPAR and CD59, in the context of their effects on viral infection." (PMID 31739586, 2019). "There is a growing body of literature showing the involvement of CD59 in viral infection and pathogenesis." (PMID 31739586, 2019). "Here, we summarize current knowledge of Ly6/uPAR proteins related to viral infection, with a focus on uPAR and CD59." (PMID 31739586, 2019). "We have found that treatment of PIV5-infected A549 cells with TGF-β resulted in an increased level of cell surface CD59 expression over that of a virus infection alone." (PMID 29693588, 2018). "Most overexpressed proteins are involved in immune response, as T-cells activation and functions (CD59, IL12A) or the response to bacterial and viral infections (CTSD, TRIM22)." (PMID 25594007, 2014). "However, some of these proteins also are involved in immune response and inflammation, as T-cells function and activation (CD59, IL12A); others are involved in the response to bacterial and viral infections (CTSD, TRIM22)." (PMID 25594007, 2014). "In mice, however, lack of CD59 does not lead to GBS following viral infection (Karbian and Mevorach, unpublished data) as Crry may prevent complement activation." (PMID 37875972, 2023). "While there are no known autoantibodies in patients with primary CD59 deficiency, nonfunctional CD59 allows spontaneous uncontrolled complement activation that results in severe demyelination and conduction block in the PNS following viral infection and possibly additional triggers." (PMID 37875972, 2023).
colorectal cancer (9 papers, 1993 to 2023). A primary or metastatic malignant neoplasm that affects the colon or rectum. "Regarding CD59 as a natural T-cell ligand involved in cognate T-cell-target-cell interaction, however, loss of CD59 might well be a selection advantage, provided that tumour antigen-mediated T-cell toxicity in colorectal carcinoma exists." (PMID 7692919, 1993). "Strategy of CD59 blockade is showing promising results, where ex vivo treatment of colorectal cancer patients’ T-cells with CD59-specific antibodies, MEM-43, and HC-1 has shown significantly enhanced antitumor immune response." (PMID 33344222, 2020). "IHC studies of tumour samples from various stages of colorectal cancer, however, showed that CD59 and CD55 expression is far less frequent than seen with our tumour cell lines." (PMID 15655555, 2005). "The silencing of CD59 in HT-29 cells promoted cell sensitivity to the chemotherapeutic drugs 5-fluorouracil and oxaliplation by promoting apoptosis and blocking G0/G1 phases, which provided a guidance for combination chemotherapy of colorectal cancer." (PMID 30636930, 2019). "Since CD46 was consistently expressed in colorectal carcinomas the low expression or even lack of CD59 in a subset of tumours might not lead to critical complement-mediated attack of CD59-negative tumour cells." (PMID 7692919, 1993).
ovarian carcinoma (9 papers, 2005 to 2023). A malignant neoplasm originating from the surface ovarian epithelium. "Membrane-bound CRPs (mCRPs), such as CD46, CD55, and CD59, are expressed by ovarian cancer tumors and cell lines." (PMID 34359708, 2021). "The decrease in the levels of CD59 in the urine of patients with bladder cancer, pancreatic ductal adenocarcinoma and ovarian cancer has been previously reported." (PMID 22949810, 2012). "In case of the 19 kDa albumin fragment, interaction appeared to be detected only in the pooled urine of patients with ovarian carcinoma compared to that of the controls, while the inverse was observed for CD59, kininogen-1 and the 39 kDa fragment of ITIH4." (PMID 21083881, 2010). "To investigate whether the tumour cells' relative resistance to C could be due to the expression of membrane regulators CD46, CD55 and CD59, we performed immunohistochemical analysis of tumour cells isolated from two patients with ovarian cancer." (PMID 15726105, 2005). "In ovarian cancer, the neutralization of CD46, CD55, and CD59 in combination with the anti-HER2 monoclonal antibodies trastuzumab and pertuzumab induces tumor cell killing in vitro." (PMID 34359708, 2021). "The utility of CD59 and MM9 in AV-binding EVs as ovarian cancer biomarker will have to be further evaluated in large patient cohort studies for their specificity and sensitivity." (PMID 28607529, 2017). "The proteomic profiling of urine samples demonstrated reduced levels of CD59, kininogen-1 and a 39 kDa ITIH4 fragment, as well as the enhanced excretion of a 19 kDa fragment of albumin in patients with ovarian carcinoma compared to control women." (PMID 21083881, 2010). "When taken as overall, the levels of CD59, kininogen-1 and ITIH4 fragment were significantly lower in ovarian carcinoma patients by 3.6-, 2.5- and 1.9-folds, respectively, compared to those excreted by the control subjects." (PMID 21083881, 2010). "The immunoblotting experiments showed that the cultured ovarian cancer cells can shed the C regulators CD46, CD55 and CD59 into the culture medium." (PMID 15726105, 2005). "The different altered levels of CD59, kininogen-1 and fragments of ITIH4 and albumin in the urine of patients with ovarian carcinoma, relative to the controls, was confirmed when their 2-DE urine protein profiles were subjected to image analysis using the Image Master 2 D Platinum Software 7.0." (PMID 21083881, 2010). "Notably, CDC50A, not CD59, was selected as a potential surface biomarker for epithelial ovarian cancer-initiating cells because of the more reasonable proportion (nearly 1%) of positive cells." (PMID 35982417, 2022). "In the present proteomic profiling study, the significant reduced excretion of CD59, kininogen-1 and a 39 kDa fragment of ITIH4, and the enhanced levels of a 19 kDa fragment of albumin were detected in the urine samples of patients with ovarian carcinoma relative to those of the control subjects." (PMID 21083881, 2010). "Significant reduced levels of CD59, kininogen-1 and a 39 kDa fragment of inter-alpha-trypsin inhibitor heavy chain H4 (ITIH4), and enhanced excretion of a 19 kDa fragment of albumin, were detected in the urine of patients with ovarian carcinoma compared to the control subjects." (PMID 21083881, 2010). "CD59, kininogen-1 and fragments of ITIH4 and albumin may be used as complementary biomarkers in the development of new noninvasive protocols for diagnosis and screening of ovarian carcinoma." (PMID 21083881, 2010).
Alzheimer disease (8 papers, 2016 to 2025). A progressive, neurodegenerative disease characterized by loss of function and death of nerve cells in several areas of the brain leading to loss of cognitive function such as memory and language. "Reduced CD59 expression has also been linked to neurodegeneration in Alzheimer's disease, bronchiolitis obliterans syndrome, and neuromyelitis optica spectrum disorder." (PMID 40739794, 2025). "The CD59 gene is slightly upregulated in neurons and glial cells in neuro-degenerative diseases associated with inflammation like Alzheimer's disease." (PMID 41542229, 2024). "Expression of GPI-anchored CD59 has been shown to be neuroprotective in neurons and decreased expression has been reported in the brains of patients with Alzheimer’s Disease (AD), and aberrant Glypican processing has been detected in the context of AD and Niemann-Pick Disease." (PMID 28103900, 2017). "Additionally, neuron cells including inhibitory neuron, and excitatory neuron in Alzheimer’s disease displayed downregulated GABRA1 expression and upregulated CD59, a complement regulatory protein, indicating increased complement activation." (PMID 39897171, 2024).
Hyperglycemia (8 papers, 2016 to 2025). An increased concentration of glucose in the blood. "Hyperglycemia causes glycation of CD59 (glycated CD59), which leads to complement-mediated glomerular damage." (PMID 40310350, 2025). "Plasma glycated CD59 (pGCD59) is an emerging biomarker which has shown promise in identifying hyperglycaemia during pregnancy and has been associated with the risk of delivering an LGA infant." (PMID 36309618, 2023). "As previously noted, hyperglycemia can cause glycation of CD59 which normally inhibits MAC complex formation." (PMID 33553201, 2020). "It has also been shown that both a deficiency and glycosylation of CD59 can lead to functional impairment and an autoimmunity response, which may warrant future consideration in relation to hyperglycemia during diabetic states." (PMID 31133884, 2019). "This interpretation is supported by histopathological and experimental studies demonstrating that hyperglycemia-induced glycation leads to the inactivation of CD59, a key regulator that prevents the formation of the MAC." (PMID 40648962, 2025). "Plasma glycated CD59 (pGCD59) is an emerging biomarker which has shown promise in identifying hyperglycaemia during pregnancy." (PMID 36309618, 2023). "Glycation-induced inactivation of CD59 leads to enhanced complement activity and is involved in the pathogenesis of hyperglycemia mediated end-organ complications." (PMID 33553201, 2020).